BCL2 (BCL2 apoptosis regulator)
Diseases named in the same sentence as BCL2 in open-access papers (continued):
Sharing a sentence is not in itself a finding about the gene and the disease.
depression (continued). "Here, in line with the view that genetic factors are critical determinants of mood control, we present our findings to show that deficit of a BCL-2 (B-Cell Lymphoma 2) family member BLM-s (BCL-2 like molecule, short transcript isoform) causes anxiety- and depression-like behavior." (PMID 36163151, 2022). "Accordingly, Blm-s−/− mice would be expected to exhibit increased BCL-2 activity, which would lead to an antidepressive phenotype as previously reported rather than causing depression." (PMID 36163151, 2022). "Bcl-2 and Bax, as one of the last pathways of apoptosis, are closely related to depression." (PMID 35873590, 2022). "For example, TNF, TLR4, IL-2, BCL-2, etc., are closely related to inflammation, and these targets may be the key targets of Hyp, the main active component of HP, in the treatment of depression." (PMID 36556951, 2022). "Bcl-2 suppress while Bax promotes neuronal apoptosis, which is involved in the onset of depression." (PMID 34177485, 2021). "Cys C induces neuronal apoptosis by increasing the level of active caspinase-9 protein and decreasing the level of B-cell leukemia 2 (Bcl-2) in the Jun-terminal kinase (JNK) dependent pathway, which may be an important risk factor for depression." (PMID 34789194, 2021). "Luteolin may influence BDNF and its downstream apoptotic proteins such as Bax and Bcl-2 to significantly combat depression." (PMID 30625977, 2019). "In particular, it has been demonstrated in animal models that psychosocial stress results in depression-like behavior through the activation of oxidative and apoptotic mechanisms, including increased ROS levels, lipid peroxidation, reduced Bcl-2 expression, and increased caspase-322." (PMID 29760952, 2018). "Moreover in the post-MI depression group, there was a greater up-regulated Bax:Bcl-2 ratio compared with the MI group." (PMID 25471226, 2014). "There was an up-regulated Bax:Bcl-2 ratio in the depression, MI and post-MI depression groups." (PMID 23394076, 2013). "Furthermore, in the post-MI depression group there was a significantly higher ratio of Bax:Bcl-2 than in the depression and MI groups (P < 0.01), and in the MI group there was a significantly higher ratio of Bax:Bcl-2 than in the depression group (P < 0.01)." (PMID 23394076, 2013). "We observed that there was an increased myocardial Bax:Bcl-2 ratio in the depression, MI and post-MI depression groups, this was particularly so in the latter group, where there was a greater Bax:Bcl-2 ratio which is important in determining a cell's vulnerability to apoptosis." (PMID 23394076, 2013). "In models of depression, 15 Hz rTMS for seven days ameliorated depressive-like behaviors and upregulated hippocampal CB1R, BDNF, and Bcl-2/Bax expression." (PMID 41440017, 2025). "The results indicated that Bax and Bcl-2 were up-regulated, which further confirmed the impairment of hepatic cells in CUMS-induced depression." (PMID 27006086, 2016). "The ratio of Bax:Bcl-2 (mean ± SEM) in the depression, MI and post-MI depression groups was statistically significantly larger than in the sham group (P < 0.05)." (PMID 23394076, 2013). "In addition to BLM-s, other BCL-2 family members have been reported to be involved in mood disorders as exemplified by dysregulated prosurvival BCL-2 and BCL-xL in anxiety, depression, or bipolar disorders in humans." (PMID 36163151, 2022). "The expression levels of miRNAs were detected by qRT-PCR, and the expression levels of Wnt2, depression-impacted proteins (GFAP, BDNF, CREB), brain neurotransmitters (5-HT, NE, DA) and apoptosis-related proteins (Bax and Bcl-2) were evaluated by qRT-PCR and western blot." (PMID 33927285, 2021). "In our study, we found that the combination therapy of REMSD and fluoxetine reversed the effects of depression on aggravating damage and promoting apoptosis in the hippocampus, upregulating the expressions of Bax, P38 MAPK, cFos, and ADAR2 expressions, and downregulating those of Bcl-2 and PI3K." (PMID 34335318, 2021).
depression (continued). "It is reasonable to believe that miR-16 may play a crucial role in the development of depression via simultaneously modulating the expression of multiple genes with different physiological functions, such as BDNF’s role in neurogenesis and BCL-2′s involvement in neuron survival and apoptosis." (PMID 23056528, 2012).
Obesity (35 papers, 2012 to 2025). Accumulation of substantial excess body fat. "Adipose‐specific MTCH2 ablation enhances brown/beige adipose thermogenesis through Bcl‐2‐dependent autophagy, promoting energy expenditure and counteracting obesity‐associated metabolic disorders." (PMID 40051328, 2025). "This increased Bax/Bcl-2 ratio caused by obesity activated the mPTP opening and increased the cytochrome c and cleaved caspase-3 levels, consequently inducing DNA fragmentation, as previously demonstrated." (PMID 30347719, 2018). "The two SNPs rs6795735 (ADAMTS9-AS2) and rs12454712 (BCL2) were previously reported to be associated with both obesity and T2D29,37,38." (PMID 29180724, 2017). "In conclusion, transgenic overexpression of Bcl-2 protects islets from cell death caused by obesogenic conditions and improves glucose-induced insulin secretion during obesity." (PMID 26064977, 2015). "Furthermore, exercise training not only enhances muscle biosynthesis but also reduces markers of muscle degradation, such as Atrogin‐1 and MuRF‐1, and protects against early mitochondria‐mediated apoptotic signaling caused by obesity (BAX/Bcl‐2 ratio and caspase‐3 expression)." (PMID 38684378, 2024). "The results revealed a strong positive correlation for all genes with obesity in EAC except for Bcl-2 and Bcl-XL where there was a strong correlation but mor towards the non-obese patients." (PMID 39395071, 2024). "Anti-apoptotic therapy is useful in such conditions, and a decrease in the correlation of Bcl-2 and Bcl-XL with obesity suggests decreased anti-apoptosis with obesity." (PMID 39395071, 2024). "We reported significant up-regulation in mRNA expression of Beclin1, ULK1, and BCL2 in the patients with obesity." (PMID 37226085, 2023). "Considering mRNA expression, Beclin1 (p = 0.0002), ULK1 (p < 0.0001), and BCL2 (p = 0.0101) were significantly upregulated in the group with obesity compared to the normal-weight group." (PMID 37226085, 2023). "Here, for the first time, we examined the association between obesity, relative sperm telomere length (STL) and autophagy-related mRNA levels such as Beclin1, AMPKa1, ULK1, BAX, and BCL2." (PMID 37226085, 2023). "Here, for the first time, we evaluated changes in autophagy-related genes (AMPKa1, Beclin1, ULK1, BAX, and BCL2) mRNA expression in spermatozoa from patients with obesity." (PMID 37226085, 2023). "Regarding mRNA expression, there was considerable upregulation of Beclin1, ULK1, and BCL2 in the group with obesity compared to the normal-weight group." (PMID 37226085, 2023). "Compared with the control group, BCL-2 in the obesity group showed a lower level, but caspase-3 showed a higher level." (PMID 35600958, 2022). "Here, molecular docking was used to reveal the potential binding mode between the obesity-related apoptotic markers (e.g., caspase 3, Bax, and Bcl-2) and quercetin, a compound with the highest degree of connections in the compound–target network." (PMID 33364948, 2020). "Transcript level of pro-apoptotic molecules such as cMyc, Casp9 and Bax were increased, whereas the level of Bcl-2 mRNA was decreased in MAIT cells during obesity." (PMID 32709874, 2020). "Previous studies also demonstrated that obesity-induced cell apoptosis by increased Bax level, decreased Bcl-2 level, and impaired brain mitochondrial function, which were also seen in the present study." (PMID 29316965, 2018). "In this context, overexpresison of the prosurvival protein Bcl-2 improved β-cell function in a mouse model of obesity." (PMID 26064977, 2015). "Conversely, the mRNA and protein expressions of Bcl-2, an anti-apoptotic biomarker, were significantly lower in obesity than in control and obese reduction, and notably lower (only in protein level) in obese reduction than in control (p<0.008)." (PMID 22784636, 2012).
Obesity (continued). "With this in mind, our purpose was to examine the association between obesity, relative STL, mRNA expression of autophagy-related genes (Beclin1, AMPKa1, ULK1, BAX, and BCL2), values of semen parameters, sperm DNA integrity, chromatin maturation, apoptotic changes, and intracellular ROS levels." (PMID 37226085, 2023). "Regarding this topic, the verified truth is that in obesity, free fatty acids produced from adipose tissue stimulate the death of pancreatic cells by an endoplasmic stress response and suppress the expression of the antiapoptotic protein BCL2." (PMID 37534085, 2023). "Mice with a diet with high fat and high dose of resveratrol during sarcopenia with obesity could increase skeletal muscle mass and the expression of mitochondrial capacity connected in Bcl‐2 and PI3K/AKT." (PMID 35961944, 2022). "Obesity increases the mitochondrial release of cytochrome c to the cytoplasm due to impaired mitochondrial balance between pro-apoptotic proteins (Bax) and anti-apoptotic proteins (Bcl-2, Bcl-XL)." (PMID 35972578, 2022). "Obesity alters the Bcl-2/Bax ratio in the testis, boosting Bax while decreasing Bcl-2 expression." (PMID 35054403, 2021). "Immunohistochemical analysis (using the indirect avidin-biotin peroxidase method) and morphometric evaluation of the expression of the antiapoptotic protein Bcl-2 and the proapoptotic protein Bad in liver cells of studied animals at different stages of obesity and DM2 were carried out." (PMID 33659827, 2020). "Interestingly, not only the pro-apoptotic, but mRNAs of two anti-apoptotic genes, Bcl-2 and Bcl-xl, were also induced during diet-induced obesity." (PMID 31165747, 2019). "In addition, the expression of proapoptotic caspases (CASP3, CASP7, CASP8, and CASP9) is increased, while the expression of Bcl2 (an antiapoptotic factor) is decreased in obesity." (PMID 28607631, 2017). "However, exercise training attenuated the obesity-induced apoptotic signaling, demonstrating that the Bax/Bcl-2 ratio, mPTP opening sensitivity, cytochrome c level, and cleaved caspase-3-positive cells in the obese skeletal muscles were reduced by exercise training." (PMID 30347719, 2018). "HFD-induced obesity led to increased TNF-α, caspase-3, and Bax and decreased Bcl-2 expression levels in heart tissue." (PMID 40292260, 2025). "In obese Zucker-fa/fa rats, BCL-2 mRNA levels were lower than in control rats, and BAX mRNA increased with the development of obesity." (PMID 39596317, 2024). "In the placental tissues, the obesity group had higher concentrations of LPS, TLR4, and caspase-3 and lower concentration of BCL-2." (PMID 35600958, 2022). "Conversely, the Bcl-2 levels were significantly greater (by 40%) in the HFD + EX group than in the HFD group (p < 0.05), suggesting that aerobic exercise training for 12 weeks protected against obesity-induced early mitochondria-mediated apoptotic signaling." (PMID 30347719, 2018). "In obesity, BAT cell apoptosis is increased due to the decrease in Bcl2 and increase in TNF-α; however, low temperature can upregulate the Bcl2 gene expression and may protect BAT against apoptosis in cold situations." (PMID 28607631, 2017). "The correlation analysis revealed a positive correlation of apoptotic factors Bad, Bak, and Bax, anti-apoptotic factors Bcl-2 and Bcl-XL, PKC-δ, inflammatory mediators AKT and NF-κB, IGF-1, proliferation marker Ki-67, and regulators of apoptosis cIAP2 and FLIP with obesity." (PMID 39395071, 2024).
Obesity (continued). "Additionally, understanding how the BCL2/BAX ratio influences adipose tissue and ASCs, respectively, function in aging horses could provide valuable insights into managing age-related diseases in equines, including obesity, metabolic syndrome, and insulin resistance." (PMID 40646808, 2025).
acute kidney injury (32 papers, 2008 to 2026). Sudden and sustained deterioration of the kidney function characterized by decreased glomerular filtration rate, increased serum creatinine or oliguria. "Genetically engineered mice with blocked expression of BCL-2 led to excessive apoptosis of the metanephric blastema causing polycys-tic kidneys and severe renal failure." (PMID 21689023, 2011). "Swimming for 8 weeks in rats with hypertension-induced renal failure decreased Bax and increased Bcl2." (PMID 36123655, 2022). "In this study, we showed, for the first time, that hyperbaric oxygen preconditioning upregulates heme oxygenase-1 and anti-apoptotic Bcl-2 protein expression in postischemic acute kidney injury induced in spontaneously hypertensive rats." (PMID 33573145, 2021). "Renal tubular expression of Bcl-2 is decreased by severe cellular stimuli, and in acute kidney injury in vivo." (PMID 30823876, 2019). "In conclusion, using HK-2 cells, we showed that Sirt5 attenuated cisplatin-induced acute kidney injury by activating Nrf2 and Bcl-2." (PMID 31815138, 2019). "Under ER stress, CHOP downregulates the expression of Bcl-2, sensitizing cells to apoptosis, resulting in renal functional and pathological damages in acute kidney injury." (PMID 26942460, 2016). "In addition, upregulated miR-543 aggravates renal tubular injury in septic acute kidney injury by directly targeting B-cell lymphoma 2 (BCL2), thereby promoting inflammation and apoptosis." (PMID 41602333, 2026). "Thus, the aim of this study was to evaluate the effects of HBO preconditioning on HO-1, pro-apoptotic Bax and anti-apoptotic Bcl-2 proteins expression, in postischemic acute kidney injury induced in normotensive Wistar and spontaneously hypertensive rats." (PMID 33573145, 2021). "Changes in the PANoptosis-related proteins BCL2, Bax, ASC, RIP3, and MLKL were measured in WT and Nrf2−/− mice treated with AME for the treatment of cisplatin-induced acute kidney injury." (PMID 40110131, 2025). "This study investigated the efficacy of geraniol to prevent methotrexate-induced acute kidney injury and via scrutinizing the Keap1/Nrf2/HO-1, P38MAPK/NF-κB and Bax/Bcl2/caspase-3 and -9 pathways." (PMID 34889889, 2021). "In a cisplatin-induced lethal model of acute kidney injury, several injections of MVs derived from MSC increased anti-apoptotic gene expression, including Bcl-2, in tubular epithelial cells." (PMID 31852535, 2019). "In a septic acute kidney injury mouse model, curcumin showed anti-inflammatory capacity and attenuation of apoptosis by JAK2/STAT3 and NF-κB signaling pathway inhibition, resulting in increased levels of Bcl-2 and decreased levels of Bax and caspase-3." (PMID 39203857, 2024). "SERPINA4 and SERPINA5, but not BCL2 and SIK3 are associated with acute kidney injury in critically ill patients with septic shock." (PMID 35874763, 2022). "For instance, in acute kidney injury in septic rats, the competitive binding of lncRNA HOX transcript antisense RNA (HOTAIR) and miR-34a results in the regulation of Bcl-2 expression, and overexpressing HOTAIR restrains apoptosis of renal tissues, thereby lowering acute kidney injury in septic rats." (PMID 34592882, 2021). "Mice globally lacking Bcl–2 (Bcl–2 -/-) are small in stature and succumb to renal failure shortly after weaning as a result of renal hypoplasia/cystic dysplasia." (PMID 26444547, 2015).
acute kidney injury (continued). "Similar to aerobic exercise, the previous study also showed that IF reduced Bcl-2 expression in rats without acute kidney injury (AKI), although not significantly." (PMID 38786985, 2024).